INS (insulin)
Diseases named in the same sentence as INS in open-access papers (continued):
Sharing a sentence is not in itself a finding about the gene and the disease.
diabetes (continued). "Prostasin levels in individuals without diabetes correlated positively and significantly with fasting blood glucose levels, plasma insulin levels and HOMA2-IR even after adjusting for potential confounders (standardised β coefficients of 0.14, 0.17 and 0.18, respectively; all p<0.0001)." (PMID 35922613, 2022). "Patients with this type of diabetes (approximately 5% of all diabetes cases) are treated with various types of exogenous insulin (short-, medium-, and long-acting insulin) because without insulin, they would not be able to survive." (PMID 35885378, 2022). "Compared with the group without FoH, the group with FoH had a longer duration of insulin use (P < 0.001), longer duration of diabetes (P = 0.029), more diabetes complications (P = 0.005), and a larger proportion of diabetic retinopathy (P = 0.032) and diabetic peripheral neuropathy (P = 0.002)." (PMID 36434039, 2022). "Furthermore, the elevation of blood glucose levels does not definitively indicate diabetes, and additional indices of glucose homeostasis need to be reported (e.g., glucose tolerance and insulin tolerance testing)." (PMID 35657616, 2022). "It will be of particular interest to examine whether hepatic insulin degradation per se will predict conversion of nondiabetic subjects to frank diabetes." (PMID 35163746, 2022). "In 1923, August Krogh, whose wife had diabetes mellitus, asked for the authorization from the University of Toronto to bring insulin to Scandinavia and founded the nonprofit Nordisk Insulin Laboratory, beginning the production of insulin to be placed on the market." (PMID 35741464, 2022). "However, PCPs are not trained on the specifics of diabetes management, including the nuances of insulin dosing and diabetes technology management." (PMID 36589850, 2022). "Moreover, the medication intake in each category analysed was significantly higher in patients with tongue lesions, with the exception of ATC H (systemic hormonal preparations, excluding sex hormones and insulin) (p=0.056) and ATC A10 (drugs used in diabetes) (p=0.099)." (PMID 34874926, 2022). "We also aim to compare glycemic control between the two types of diabetes (autoimmune diabetes mellitus and negative-autoimmunity diabetes mellitus), considering HbA1c and insulin requirement during the first year after diagnosis at t1 (+6 months from onset) and t2 (+12 months from onset)." (PMID 35769090, 2022). "These benefits have led the American Diabetes Association to recommend CGM use for patients with diabetes who require insulin therapy and to even consider use in patients with type 2 diabetes who do not require insulin therapy." (PMID 36548330, 2022). "Therefore, the correlation between SerpinB1 and insulin sensitivity or β-cell function in this study did not seem to be influenced by the use of anti-diabetes drugs." (PMID 36331940, 2022). "The percentage of snacks/sweets were statistically significantly different in consumption frequency, but not energy contribution among the three groups, which showed an increasing trend from the group reporting taking insulin to those with T2D not using insulin to participants without diabetes." (PMID 36014790, 2022). "Compared to youths without pre-diabetes (reference category), family history of T2DM was associated only with isolated IGT, while the abnormalities underlying beta cell function and insulin sensitivity were associated with either isolated IGT or any combined phenotype." (PMID 35579861, 2022). "The PVDF was implanted into alloxan-induced diabetic rats, which were used as a model of impaired insulin secretion due to pancreatic beta cell destruction rather than obesity-induced diabetes, and rats were tracked for 24 days, showing significantly improved body weight and blood glucose levels." (PMID 35683855, 2022).
diabetes (continued). "However, there are also additional findings suggesting that active vitamin D supplementation in humans improves insulin sensitivity only in patients with early diabetes, but not insulin sensitivity and β-cell function in other patients." (PMID 34807347, 2022). "Similarly to non-pregnant individuals with diabetes mellitus treated with insulin, mothers affected by GDM who are on insulin are also more likely to have a confirmed SARS-CoV-2 infection irrespective of their BMI." (PMID 36079820, 2022). "In addition, data regarding classification of diabetes severity (i.e. insulin-dependent versus not insulin-dependent) were not available for consideration in this study." (PMID 36158330, 2022). "As the government continues to support patients with diabetes who use traditional methods by distributing glucometers for free to every patient with diabetes in their facilities, it also started providing modern diabetes technologies, such as FGM and insulin pumps, mostly for type 1 patients." (PMID 35719798, 2022). "In addition, the authors observed that the use of LA with insulin in patients with diabetes showed a synergistic effect against SARS-CoV-2, therefore, LA treatment will be beneficial against COVID-19 in patients with diabetes." (PMID 35739949, 2022). "The robust improvement of insulin sensitivity resulted from the prevention of IR cleavage by inhibition of MT1-MMP nicely illustrates that MT1-MMP-mediated cleavage of IR is the major driving force in eliciting insulin resistance in both physiological aging and diabetes." (PMID 35768470, 2022). "However, the TyG index performed better in assessing insulin resistance and allowing earlier identification of the development of diabetes and its complications than HOMA-IR regardless of the use of insulin-related medication and diabetes status." (PMID 36601005, 2022). "When insulin and glucagon positive cell numbers were added together, the cell number in the diabetes group was dramatically decreased compared to the control group (p < 0.001), both GQD and metformin groups had higher cell numbers than the diabetes group (P < 0.05)." (PMID 35858880, 2022). "However, there remains a lack of acceptance of insulin initiation and adherence to insulin, thereby contributing to poor diabetes control." (PMID 35172774, 2022). "In summary, we demonstrated that Cyp2r1 is repressed by the STZ-induced diabetes in the liver, and the effect could not be corrected by insulin therapy." (PMID 35524739, 2022). "INSR and insulin also had a negative correlation in the normal glucose tolerance group in the FUSION human cohort, suggesting that this consistent association is independent of pathological changes or diabetes." (PMID 34921686, 2022). "We specifically aimed to identify one phenotype of AD: individuals with non-insulin-dependent diabetes and no history of obesity, metabolic syndrome, or other known cause of insulin resistance, which we have termed “insulin-sufficient, non-metabolic” (ISNM) diabetes." (PMID 36508462, 2022). "Notably, various other events such as obesity, diabetes, and LPS-induced inflammation alter the permeability of the BBB to insulin, which may lead to changes in insulin signaling and related functions in the brain." (PMID 36430894, 2022). "Moreover, most of the PCPs (68.8%) believe that lack of education about diabetes and its complications among patients is another barrier among patients to accept insulin." (PMID 36554673, 2022). "Type 2 Diabetes Mellitus (T2DM) is defined by the World Health Organization as a metabolic disorder of multiple etiology characterized by chronic hyperglycemia with disturbances of carbohydrate, fat and protein metabolism resulting from defects in insulin secretion, insulin action, or both." (PMID 35710773, 2022).
diabetes (continued). "Therefore, we detected the FoxO1 expression in our diabetes mouse model and found that GDM-F1 male mice showed increased expression of FoxO1, and in vitro experiments confirmed that exogenous insulin stimulation produced a similar tendency of FoxO1 as those in vivo." (PMID 35432202, 2022). "To determine whether reduced CYP8B1 activity improves insulin sensitivity, we sequenced CYP8B1 in individuals without diabetes and identified carriers of complete loss-of-function (CLOF) mutations utilizing functional assays." (PMID 36107630, 2022). "Diabetes mellitus is a threatening metabolic syndrome that occurs when the pancreas cannot produce enough insulin, or when the body is no longer able to make much of the insulin it produces." (PMID 36232871, 2022). "A person with Type 1 diabetes mellitus (T1DM) is triggered by inadequate or no insulin secretion." (PMID 36144587, 2022). "Sedentary increases the production of reactive oxygen species, leading to a chronic state of oxidative stress, in type II diabetes, oxidative stress changes the secretion of insulin and the sensitivity of hormones to target cells, so the lack of exercise increases the prevalence of diabetes." (PMID 36110415, 2022). "Neither a previous diabetes diagnosis nor laboratory parameters of glucose metabolism (glucose, insulin and C-peptide concentrations in an oral glucose tolerance test) were found to be independently associated with IGFBP7 concentration in the multivariate analysis." (PMID 35204773, 2022). "Diabetes mellitus does not seem to play a role in hypoglycemia during insulin treatment." (PMID 36584121, 2022). "Compared with CD-fed mice, HFD-fed mice showed increased blood levels of glucose and insulin under fasting conditions and increased plasma HOMA-IR, an indicator of insulin resistance; administration of B. wexlerae decreased these diabetes indicators in HFD-fed mice." (PMID 35982037, 2022). "Moreover, they are also recognized as adipocytokines with fairly negative impacts on insulin signaling; the combination of TNF-α and IL-6 had an impact on progressive pancreatic β-cell loss during the progression of diabetes." (PMID 36299624, 2022). "Insulin access and affordability are critical barriers to preventing acute and long-term diabetes complications, yet people with diabetes report lack of support and resources from health care providers, pharmaceutical companies, insurance companies, hospital systems, and pharmacies." (PMID 35436214, 2022). "A complementary phase 1 follow-up clinical trial will also be conducted in the United States to investigate its therapeutic potential and side effects in T1D patients who use insulin and have no other diabetes-related health complications (Clinicaltrials.gov identifier: NCT04590872)." (PMID 35563276, 2022). "Additionally, the intravenous glucose injections did not significantly affect the insulin balance during hemodialysis in patients with diabetes." (PMID 36558521, 2022). "Diabetes mellitus is a metabolic disease characterized by hyperglycemia resulting from insufficient or absent insulin secretion from the pancreas, with or without concomitant impairment of insulin action, or both." (PMID 36289594, 2022). "Some people with diabetes who could not afford insulin went to the emergency room to treat hyperglycemia as a quick solution, leading to additional health care expenses, despite obtaining no-cost insulin coupons or insulin from that visit." (PMID 35436214, 2022). "However, in rabbits with alloxan monohydrate induced diabetes mellitus, systemic administration of insulin does not lead to a significant improvement in RTQ values compared to hyperglycaemic animals." (PMID 36276721, 2022). "Notably, CKD patients had higher proportions on insulin (33.0%), insulin secretagogues (27.6%), and DPP4i (21.3%) compared to patients with diabetes without CKD." (PMID 35606699, 2022).
diabetes (continued). "Interestingly, insulin infusion can substantially increase left ventricular ejection fraction (LVEF) in response to submaximal dynamic exercise among both healthy subjects and patients with diabetes." (PMID 36289641, 2022). "%HbA1c was the only measure of glycemia collected in this cohort and limited information was available regarding the use of specific diabetes medications (i.e., categories included: no use of diabetes medications, use of oral agents, use of insulin, or use of both insulin and oral agents)." (PMID 35583495, 2022). "Among the treatments for type 1 diabetes mellitus (T1DM), Continuous Subcutaneous Insulin Infusion (CSII) is a device that infuses insulin through the subcutaneous tissue in an uninterrupted manner and that comes closest to the physiological secretion of insulin." (PMID 35183150, 2022). "In agreement with previous literature, diabetes distress in our study was significantly higher in patients on insulin treatment than those not on insulin, suggesting the ability of the tool to discriminate between those who had greater likelihood of having distress than those with least likelihood." (PMID 35022493, 2022). "Type 1 diabetes mellitus (T1DM) is an autoimmune disease that originated from the destruction of β-cells, whereas T2DM is the consequence of a failure of β-cells to produce enough insulin to overcome systemic insulin resistance, frequently associated with obesity, inactivity, and aging." (PMID 35741464, 2022). "When people with diabetes could not afford insulin, the campaign requestors described rationing insulin doses and/or food to avoid diabetic ketoacidosis and fear of dying." (PMID 35436214, 2022). "Moreover, basal FGF21 secretion, especially in response to insulin dose, in patients with type 1 diabetes mellitus (T1DM), has not been well examined." (PMID 35192641, 2022). "Blood sugar levels stay high in those with diabetes; the most prevalent forms are type 1 DM (T1DM; 5%) and type 2 DM (T2DM; 95%), which are brought on by problems with the pancreas’ production of insulin or by the body’s inability to effectively use the insulin it produces." (PMID 36204023, 2022). "Although CGM technology can empower and motivate patients with type 1 diabetes mellitus who are accustomed to routine self-monitoring of blood glucose to guide insulin dosing, CGM technology may enhance diabetes-related distress, which is a known barrier to T2DM self-management." (PMID 35107429, 2022). "The observed rise in blood and hepatic glucose with a concomitant rise in plasma insulin concentration, plasma α-amylase and DPP-IV activities in diabetic rats was consistent with the findings of other researchers who used the HFD and low dose STZ diabetes induction model." (PMID 35739183, 2022). "Moreover, the GD patients with COVID-19 required pharmacological treatment for diabetes more often than the pregnant women without the infection did; medications included insulin, metformin, or both." (PMID 36676978, 2022). "Moreover, demographic features and insulin ones did not present the additional performance advancement for diabetes forecasting." (PMID 36572938, 2022). "For example, continuous glucose monitoring wearables for patients with diabetes or flash glucose sensor technology, which do not require a fingerpick to measure insulin levels, will allow people to manage their diabetes more efficiently, and thus increase their ability to continue to work." (PMID 35862177, 2022). "The inability of the body to completely utilize the glucose produced by cells due to improper secretion of insulin in pancreas is diabetes; if the produced insulin is not sufficient to convert the entire glucose into energy then the disease is characterized as Type 2 diabetes." (PMID 34996986, 2022). "Therefore, it is important for individuals without diabetes to understand their glucose metabolism status, i.e., insulin sensitivity and secretion, and to take appropriate measures for preventing diabetes." (PMID 36118835, 2022).
diabetes (continued). "Second, information on diabetes medication or insulin therapy and type of diabetes could not be obtained." (PMID 35627961, 2022). "A sensitivity analysis was performed based on whether the participant was diagnosed with diabetes, and the relationship between PA and insulin was observed in participants without diabetes." (PMID 35185617, 2022). "Management of diabetes is complex and needs to follow several strategies such as consumption of balanced diet, knowledge of diet‐related factors that may help in controlling blood glucose level (BGL), physical exercise, and, if needed, proper use of insulin." (PMID 36171777, 2022). "We have shown that maternal RUPP has negative and sex-specific impacts on the regulation of insulin, glucagon and ghrelin in offspring and that, as young adults, male rats may be more prone to develop diabetes." (PMID 36109770, 2022). "In the THA group the contract type of the PT clinic, the procedure volume and COPD were no longer statistically significant predictors, while insulin use in diabetes patients entered the model as a statistically significant need factor in the prediction of post-discharge PT utilization (β = 2.36)." (PMID 35986285, 2022). "The time required to meet diabetes education and support needs of older adults using telemedicine, including needs related to the use of new and remote monitoring devices and insulin delivery systems, is important to understand but has not been previously reported." (PMID 35720451, 2022). "Although we did not include T1DM as an outcome, most of the studies that investigated glucose, insulin, diabetes or MetS outcomes did not report whether they had accounted for potential T1DM cases in their study sample." (PMID 35954531, 2022). "Studies have indicated that peripheral IL-6 blockade with tocilizumab may improve insulin sensitivity and glycemic control in humans with and without diabetes, where plasma IL-6 is elevated." (PMID 35470093, 2022). "Third, even though we adjusted many confounders in regression models, residual confounding effects from unmeasured or unknown factors could not be excluded entirely such as the quality of diabetes management or insulin resistance." (PMID 36079863, 2022). "The role of these natural compounds, their actions on the insulin signaling pathway, and the stimulation of the glucose transporter-4 (GLUT4) insulin-responsive translocation to the plasma membrane (PM) are all crucial in the treatment of diabetes and insulin resistance." (PMID 35356248, 2022). "Interestingly, despite the decrease in insulin content at day 15 of diabetes, islet morphology, insulin and glucagon staining were not affected in NDM islets." (PMID 35180212, 2022). "In addition, participants who developed retinopathy were more likely to be older, belonged to the white race, assigned to the standard treatment arm, had a longer duration of diabetes, higher levels of HDL, SBP, but lower levels of BMI, triglyceride, RC, eGFR, and were less likely to be on insulin." (PMID 35668633, 2022). "In the study of diabetes, the T2DM rats induced by high-fat and high-sucrose (HFD) diet combined with streptozotocin (STZ) was usually used as experimental animal models in vivo, and the STZ destroyed rat islet β-cell to simulate the state of insufficient insulin secretion." (PMID 35548575, 2022). "When administered after induction of diabetes with low-dose STZ, ABA ameliorated the efficacy of residual endogenous insulin on glycemia, resulting in a significantly reduced glycemia profile in the treated animals, and also improved the response to exogenous low-dose insulin." (PMID 35736456, 2022). "Thirty percent of patients that skipped their medications and demonstrated non-adherence may have skipped their oral diabetes medication or may have skipped a dose of their basal insulin." (PMID 35619860, 2022).